CCND1 (cyclin D1)
Diseases named in the same sentence as CCND1 in open-access papers (continued):
Sharing a sentence is not in itself a finding about the gene and the disease.
cancer (continued). "CCND1, a key factor promoting cancer cell cycle progression, survival, and proliferation, is a typical substrate of the ubiquitin‐proteasome pathway." (PMID 40145254, 2025). "We showed that serum starvation-induced G1 phase arrest in cancer cells and diminished the protein levels of 66CTG, c-Myc, and Cyclin D1, which were blocked by MG132." (PMID 40628713, 2025). "This was demonstrated by decreased β-catenin levels and reduced expression of target genes such as cyclin D1 and c-Myc, which are involved in cancer cell survival." (PMID 40725141, 2025). "Lastly, genes coexpressed with CCND1 in EC were identified and subjected to functional annotation to explore their biological roles and potential pathways involved in cancer progression." (PMID 39940659, 2025). "Immunosuppressive conditions can lead to cancer development and metastasis by promoting chronic inflammation and overexpression of cyclin D1." (PMID 40297577, 2025). "Another cucurbitacin, E, inhibited proliferation of A549 (lung), Hep3B (hepatocellular), and SW480 (colon) cancer cell lines via downregulation of cell cycle regulators, including the Wnt target gene cyclin D1." (PMID 40427472, 2025). "Cyclin D1/CDK inhibitors have been evaluated across various phases of clinical trials for both cancers and other diseases." (PMID 39948552, 2025). "The cancer-related function of cyclin D1 has been primarily studied by focusing on the phosphorylation of the retinoblastoma (RB) gene product." (PMID 38979260, 2025). "ATOX1, a key copper chaperone, has been shown to promote cell proliferation through cyclin D1 activation and facilitate cancer metastasis by accumulating at the leading edge of migrating cells." (PMID 40002764, 2025). "Cyclin D1 expression, augmented in several human cancer types has been found in over 60% of human and canine MM." (PMID 40568110, 2025). "Both receptors also activate the GSK3β/β-catenin pathway, promoting cancer-related genes (such as c-myc, cyclin D1, and VEGF)." (PMID 40430008, 2025). "The WNT pathway is well known for regulating cellular processes, such as proliferation and differentiation, with aberrant activation contributing to cancer development through β-catenin stabilization and cyclin D1 upregulation." (PMID 39910812, 2025). "Recent studies showed that some deubiquitinases interacted with CCND1 and prevented its polyubiquitination and degradation, resulting in cell cycle progression and cancer cell growth." (PMID 40145254, 2025). "Many studies have shown that STAT3 induces the transcription of genes involved in cancer cell proliferation and survival, such as CCND1, BCL2, and MYC." (PMID 41104968, 2025). "CCND1, a pivotal cell cycle regulator, exhibits overexpression in various cancer types and is correlated with an unfavorable prognosis in BC." (PMID 40575382, 2025). "CELSR2 KD resulted in a significant downregulation of cyclin D1, which is an important regulator of cell cycle and plays a central role in the pathogenesis of cancer." (PMID 41184253, 2025). "Although CDK inhibitors targeting Cyclin D1/CDK4/6 complexes have shown therapeutic potential in cancers such as breast and lung, their role in EC remains underexplored." (PMID 39940659, 2025). "Recently, FXR has emerged as a tissue-specific oncogene that modulates a range of cancer-associated genes, such as COX-2, cyclin D1 and VEGF." (PMID 40985894, 2025). "Our findings demonstrate that OTI-611 alone induces G1 cell cycle arrest, downregulates Cyclin D1, and inhibits cancer cell proliferation more effectively than chemotherapy or PARPi alone." (PMID 40072047, 2025).
cancer (continued). "In terms of cell-cycle disruption, which is a desired effect to stop cancer cell proliferation, our two ILs were effective arresting the cell cycle in the G0/G1 phase, which was accompanied by a substantial drop in cyclin D1 expression." (PMID 40981089, 2025). "Translation inhibition correlates with reduced production of cancer-promoting proteins like Cyclin D1 and c-Myc." (PMID 40952561, 2025). "CCND1 is a critical cell cycle regulator that plays an important role in the expression of several types of cancer." (PMID 40140215, 2025). "Some studies have linked BATF2 to the suppression of cell cycle regulation genes, including CCND1, through binding with AP-1 subunits in the context of cancer." (PMID 40945729, 2025). "Overexpression of CCND1 can also secrete a vascular endothelial growth factor, providing nutrients for metastasized cancer cells." (PMID 41305721, 2025). "A decrease in DILA1 expression leads to Cyclin D1 expression decline, which ends up in cancer cell growth suppression and restoration of sensitivity to tamoxifen, both in experimental cell cultures and animal models." (PMID 41348684, 2025). "The interplay between SMAD4, C-MYC, and Cyclin D1 thus forms an essential signaling network that governs the proliferative capacity of cancer cells." (PMID 40224178, 2025). "Amplifications of the Cyclin D1 gene are commonly observed in cancers, where its upregulation drives unregulated cell growth." (PMID 40224178, 2025). "Currently, research on PKMYT1 inhibitors is limited, with lunresertib being the only reported effective PKMYT1 inhibitor, capable of inducing synthetic lethality in cancers with CCND1 amplification." (PMID 40702552, 2025). "The SMAD complex then functions as a transcription factor in cancer cells, regulating the expression of genes like cyclin D1, BCL-2, and VEGF." (PMID 40485724, 2025). "When dysregulated, overexpression or otherwise aberrant accumulation of cyclin D1 can be manifest in a variety of solid human cancers, consistent with an oncogenic function." (PMID 40568110, 2025). "Deprivation of intracellular cysteine in cancer cells induced cell cycle arrest at the G0/G1 phase, accompanied by a decrease in the expression of cyclin D1 and D2 proteins." (PMID 39413876, 2024). "The copy gain regions were located on 1q21, 3q26, 11q13, and 12q15, with 33 genes located in narrow peak regions, including the Cancer Gene Census listed genes CCND1 and MDM2, both of which are frequently amplified in an Asian CCA cohort." (PMID 38877653, 2024). "When GOLPH3 and STIP1 are knocked down, they can not only inhibit the proliferation of pancreatic cancer cells, but also inhibit the expression of cyclin D1 in cancer cell." (PMID 38594465, 2024). "WB detected protein expression levels of CDK4, CDK6 and cyclin D1, which were key cell cycle proteins for cancer proliferation." (PMID 38195969, 2024). "The inhibitory effect of lycopene on the growth of cancer cells depends on the level of cyclin D1, which cuts off the transition of MCF-7 cells from the G1 to the S phase." (PMID 38539798, 2024). "In conclusion, we identified PIK3R1, CCND1, TERF2IP, SLC25A4, CAPN2, and TXN as potential markers associated with both cancer and MN." (PMID 38846934, 2024). "For instance, the overexpression of cyclin D1, observed in various cancers, propels uncontrolled cell proliferation by activating CDK4/6." (PMID 38983782, 2024). "We further explored the CCND1 genetic alteration status in human cancers in TCGA and Pan-Cancer Atlas cohorts using the cBioPortal database." (PMID 39188436, 2024). "Upregulation and activation of NF-κB contribute to unregulated cell proliferation in cancer cells, given that NF-κB transcription factors regulate the expression of cell cycle regulators such as cyclin A, cyclin D1, or cyclin-dependent kinase 6 (CDK6)." (PMID 38727313, 2024).
cancer (continued). "Mechanistically, the combination of MRTX849 and dasatinib inhibited JUN-dependent expression of ABCC1 and CCND1 in multidrug-resistant cancer cells." (PMID 39661665, 2024). "Low levels of let-7b, through the inhibition of MYC, RAS and CCND1, influence the induction of cell proliferation and growth, and thus the progression of cancer." (PMID 38473390, 2024). "CCND1 expression among the significant cancers integrated with clinical parameters using the UALCAN database." (PMID 39188436, 2024). "In cancer, documented cases of DNA amplification at 11q13, primarily likely selecting for CCND1 proto-oncogene activation, often correspond to elevated MYEOV expression and an unfavourable prognosis." (PMID 39139450, 2024). "It promotes the expression of oncogenic proteins that enhance cancer cell growth, survival, and progression such as cyclin D1, c-Myc, and insulin-like growth factor 1, while inhibiting cell cycle arrest proteins such as p21." (PMID 39742369, 2024). "We found that the cancer/normal fold change of mean CCND1 SLR values was > 1 in most cases, confirming the ability of APAtrap to report on APA events." (PMID 39527514, 2024). "The aim was to examine the relationship between FGF2 and FGFR1 and their impact on mRNA expression of P21 and CCND1, cell cycle status, and cancer stemness characteristics." (PMID 38553760, 2024). "CCND1, a key mediator of cell cycle progression, is a major protein involved in cell cycle regulation and plays a crucial role in the pathogenesis of cancer." (PMID 39739897, 2024). "Ectopic expression of Cyclin D1 in UMUC3 cells reversed ISO-induced G0/G1 growth arrest, suggesting that the downregulation of Cyclin D1 by ISO contributes to its cancer inhibitory effect." (PMID 38339062, 2024). "Although GSK-3β and Cyclin D1 are known to be involved in cell cycle regulation, their relationship in cancer cells remains controversial." (PMID 39241034, 2024). "Highlighting the significance of interactions with extracellular growth factors such as VEGFA and IGF1 in cancer growth and progression, several targets, including CCND1, WEE1, VEGFA, and CDK6, were identified to interact with two miRNAs." (PMID 39614097, 2024). "Immune infiltration and survival analyses were performed to explore the prognostic implications of CCND1 expression in various cancers." (PMID 39188436, 2024). "We investigated the survival analysis using the Kaplan Meier Plotter, Cox proportional hazards model, and log-rank test to examine the relationship between CCND1 in different types of cancer as shown in." (PMID 39188436, 2024). "Cyclin D1 is a crucial cell cycle regulator that controls unchecked cell proliferation in the development of cancer." (PMID 38370338, 2024). "Cancer preventive agents have been reported to inhibit the cyclin D1 protein and its complex, which further decreases cell proliferation by dysregulating cyc-D expression and results in cell cycle arrest." (PMID 39246660, 2024). "Studies have shown that CCND1 is an important target for several miRNAs regulating cancer development and drug resistance." (PMID 39739897, 2024). "Dysregulation of CCND1 is intricately interwoven with HNSCC, driving uncontrolled cellular proliferation—a hallmark of cancer." (PMID 37882107, 2024). "The essential G1-cyclin, CCND1, is frequently overexpressed in cancer, contributing to tumorigenesis by driving cell-cycle progression." (PMID 38191593, 2024). "In most cancers, “amplification” was the primary genetic alteration type, and the highest amplification frequency of CCND1 (34.07%) occurred in cases with ESCA." (PMID 39188436, 2024). "Through canonical and noncanonical pathways, ASPH inhibitors interrupt cell cycle progression by downregulating cyclin D1 and arresting cells in the G0/G1 cell cycle phase, thereby inhibiting the proliferation of cancer cells." (PMID 38817852, 2024).
cancer (continued). "Ccnd1 triggers the G1–S phase transition in the cell cycle by activating cyclin-dependent kinases (Cdk4 and Cdk6) and enhances the proliferation of cancer cells." (PMID 38251008, 2024). "Studies have shown that inhibition of hTERT can inhibit cyclin D1 signalling in cancer cells and also inhibit the cell cycle." (PMID 38594465, 2024). "Cyclin D1 exhibits frequent abnormalities in various human cancers and plays a crucial role in facilitating the transition from the G1 to the S phase of the cell cycle in numerous cell types." (PMID 39355840, 2024). "G4-promoted TF condensate dynamic can activate downstream oncogenes, such as CCND1, and subsequently enhance cancer progression." (PMID 38316778, 2024). "The authors demonstrated that TB promotes the proliferation of cancer cells through the influence of exosomal miR-130b-3p and miR-423-5p, which enhance the expression of Cyclin D1 and p65." (PMID 39682592, 2024). "By promoting Cyclin D1 and Bcl-2 expression, the NF-κB pathway drives cell cycle progression and promotes the proliferation of cancer cells." (PMID 39169391, 2024). "Cyclin D1 expression at the transcriptomic level increased in the cancer cells and decreased in the CSCs following shC treatment." (PMID 38474121, 2024). "Numerous studies have shown that dysregulation of CCND1 isoform expression affects various features of cancer." (PMID 39739897, 2024). "In summary, TPE-derived exosomal miR-130 and miR-423 influence cell cycle regulation by inducing an increase in cyclin D1 levels via NF-kB and by directly inhibiting p21, thereby contributing to cancer proliferation." (PMID 39337604, 2024). "CCND1 was a key factor in cell cycle regulation, and aberrantly expressed in different human cancers." (PMID 39588389, 2024). "The differential methylation analysis of CCND1 demonstrated a considerable downregulation in several cancers, including COAD, KIRC, and THCA, with COAD showing the most significant downregulation." (PMID 39188436, 2024). "Cyclin D1 (CCND1), a fundamental regulator of the cell division cycle, is one of the most often disrupted therapeutic targets in human cancer." (PMID 39077467, 2024). "Cyclin D1, a crucial cell cycle regulator which is often overexpressed in cancer, promotes entry into the S phase and cancer growth." (PMID 38474121, 2024). "CCND1 plays a pivotal role as a critical regulator of the cell cycle and holds a central position in the development of cancer by driving uncontrolled cellular proliferation." (PMID 38846934, 2024). "Our results indicated that high FGFR1 groups had elevated p21/CCND1 ratios, reduced M and S phases, and heightened cancer stemness traits, while low FGFR1 groups demonstrated less impact or a contrary trend." (PMID 38553760, 2024). "Another anti-cancer effect of curcumin is its influence on cyclin D1 levels, an important regulator of cell cycle progression." (PMID 39206407, 2024). "Cyclin D1 is a key regulator of cell-cycle progression by promoting G1–S transition and therefore provides a proliferative advantage to cancer cells." (PMID 39028933, 2024).
cancer (continued). "Regarding cell-cycle arrest, previous studies have reported that ERB-041 induced G1-phase arrest in human cancers by decreasing cyclin D1 expression, which regulates the cell-cycle transition from the G1 phase to S phase through PI3K/AKT pathway inhibition." (PMID 38473712, 2024). "Cyclin D1 is an essential regulator in the G1 phase and an oncogenic driver in cancer cells, and CDK inhibitor p21 mediates the cell cycle negatively." (PMID 38413784, 2024). "Cyclin D1/CDK4-Rb pathway has a significant role in the G1 phase, which is implicated in the development of cancer." (PMID 39161904, 2024). "Its activity is significantly heightened in various cancer contexts, and the expression of CCND1 is indispensable for the survival and proliferation of cancer cells." (PMID 38846934, 2024). "The study focuses on the role of the Fbxo4-cyclin D1 axis, commonly dysregulated in various cancers, in controlling glutamine addiction (Gln addiction) independently of known signaling pathways." (PMID 38474224, 2024). "Overexpression of cyclin D1 has been observed in a wide range of cancers, including breast cancer, lung cancer, and prostate cancer." (PMID 39246660, 2024). "Cyclin D1 (CCND1) is an important molecule in cell cycle regulation that promotes proliferation and apoptosis in human cancer cells." (PMID 38517922, 2024). "Numerous novel targets have been identified, including SOCS, STAT3, Nrf2, NF-B, cell cycle regulators cyclin D1, D2, and D3, INPs, and Wnt, which are expressed improperly in pre-cancer lesions." (PMID 39246660, 2024). "The results from the UALCAN database comparing cancer with normal tissues showed that the CCND1 promoter was hypomethylated in BLCA, HNSC, KIRC, READ, THCA, and UCEC." (PMID 39188436, 2024). "The downregulation of PRKAR1A expression increased cyclin D1 expression and the S phase length of the cancer cells." (PMID 38474121, 2024). "The effects of ASPH inhibitors on Notch1 pathway activity, cyclin D1 expression, and nuclear morphology contribute to the understanding of the multifaceted effects of these inhibitors on cancer cell behavior." (PMID 38817852, 2024). "CCND1, another key regulator of the cell cycle, plays a central role in cancer pathogenesis by driving uncontrolled cellular proliferation." (PMID 38813193, 2024). "FIRRE-HuR axis modulates the downstream molecule, cyclin D1, an important regulator of the cell cycle progression pathway of cancer." (PMID 38556083, 2024). "The discovery of six amplified (i.e., WHSC1L1, CCND1, and SOX2) and 29 deleted (i.e., NCOR1, SETD2, and CBL) cancer associated genes was highlighted." (PMID 38539567, 2024). "Reduced Ki-67 and cyclin D1 levels, as well as decreased phosphorylation of signal transducer and activator of transcription 3, occur in Il1r1Hep−/− livers, lowering cancer cell proliferation and growth." (PMID 39621069, 2024). "We propose that cyclin D1 overexpression mechanically adapts cell division to compressive environments, potentially contributing to its prevalence in cancer despite the aberrant spindles it induces." (PMID 38478555, 2024). "The genetic alteration analysis revealed that amplification was the predominant genetic alteration type in CCND1, with specific patterns observed in different cancer types." (PMID 39188436, 2024). "Cyclin Ds, including D1, D2, and D3, control cell cycle progression by mediating cell proliferation and extracellular stimulation, of which cyclin D1 (CCND1) is more attractive because of its widespread dysregulation in human cancer." (PMID 39258670, 2024). "Conversely, cyclin D1 in HCT-116 was exceptionally increased, possibly because cyclin D1 is available in two isoforms (a and b); cyclin D1b upregulation induces G1 arrest with apoptosis in carcinoma cells." (PMID 38893527, 2024). "NICD levels and Notch target genes, including Hey1, Hes1, and cyclin D1 (Ccnd1), were significantly upregulated in HG-treated Met1 cancer cells, suggesting that HG activates Notch signaling." (PMID 36707514, 2023).